BDNF (brain derived neurotrophic factor)
Diseases named in the same sentence as BDNF in open-access papers (continued):
Sharing a sentence is not in itself a finding about the gene and the disease.
Cognitive impairment (continued). "Hippocampal brain-derived neurotrophic factor (BDNF) or Neurotrophin-3 (NT-3) microinjection could partially improve the sevoflurane-induced cognitive impairment and AHN inhibition, respectively." (PMID 35309893, 2022). "Finally, EC has been shown to improve cognitive impairment, but also to elevate brain-derived neurotrophic factor (BDNF), which is a neurotropin involved in learning and memory." (PMID 35327563, 2022). "FGF2-Akt and BDNF-TrkB signaling pathways were reactivated by Rg1 in the hippocampus and prefrontal cortex to inhibit neuronal apoptosis and prevent cognitive deficits and experimental basis for the development and use of ginsenoside for anti-aging and age-related diseases." (PMID 34964700, 2022). "Previous studies also found that resveratrol upregulated the level of pCREB and prompted the BDNF expression in the hippocampus in a chronic unpredictable mild stress (CUMS) animal model and prevented CUMS-induced cognitive deficits by regulating the CREB/BDNF expression in the hippocampus." (PMID 36478990, 2022). "Indeed, more recent findings show that upregulated astrocytic BDNF production, conditioned to astrogliosis, improves cognitive deficits and recovers spine density, morphology, and markers such as PSD-95 in Alzheimer’s mice." (PMID 35955546, 2022). "The levels of 5-HT, GABA, and BDNF in the blood samples from the premature rats with cognitive impairment were significantly lower than that from the normal control group, while the serum levels of GR, CRH, IL-6, and TNF-α were significantly up-regulated in rats with cognitive problem." (PMID 36061856, 2022). "However, overexpressing BDNF in these regions protects against the cognitive deficits induced by adolescent cannabis exposure in mice." (PMID 35090576, 2022). "The study found that BDNF, as a protein with a neurotrophic effect, can improve sevoflurane anesthesia-mediated cognitive impairment of hippocampal neurons in aged rats, which may be related to the activation of the Akt signaling pathway." (PMID 36504660, 2022). "BDNF plays an increasingly important role as a biomarker not only in affective disorders, but also in cognitive impairment, such as that associated with alcohol abuse." (PMID 35740389, 2022). "Furthermore, we found that the cognitive disorder and altered intestinal microflora structure in preterm rats were associated with decreased levels of 5-HT, GABA, and BDNF, and increased levels of GR, CRH, IL-6, and TNF-α in serum." (PMID 36061856, 2022). "Previous study has confirmed that the cognitive impairment induced by sevoflurane and the decrease of BDNF expression occur in parallel, and over-expression of BDNF could be prevented it." (PMID 35309893, 2022). "Moreover, GH prevented cognitive impairment via BDNF/ERK/CREB pathways in a scopolamine-induced mouse model." (PMID 35126824, 2022). "In this context, the aim of this study was to verify the effects of a multicomponent exercise program on physical fitness and cognitive function in the elderly with mild cognitive impairment and determine the role of oxidative stress and brain-derived neurotrophic factor (BDNF)." (PMID 36092805, 2022). "The cognitive impairment in vascular dementia involved the BDNF-ERK-CREB pathway." (PMID 35743271, 2022). "The precise molecular mechanisms of BDNF and its signaling cascades that lead to neurodegeneration and cognitive impairment in Parkinson’s disease remain unknown." (PMID 35743271, 2022). "ω-3PUFAs can ameliorate cognitive impairment by upregulating BDNF in SCZ to repair neuronal damage." (PMID 36406755, 2022). "However, little is known about how the CREB/BDNF pathway in the hippocampus is involved in neuropathic pain and related cognitive deficits." (PMID 36478990, 2022). "BDNF serum concentration has been reported to correlate with the clinical symptoms of neurodevelopmental disorders such as reduced intelligence, behavioral problems, and intellectual impairment in preschoolers." (PMID 35573386, 2022).
Cognitive impairment (continued). "Furthermore, cognitive impairment caused significantly decreased levels of 5-HT, GABA, and BDNF, and increased levels of GR, CRH, IL-6, and TNF-α in rat blood." (PMID 36061856, 2022). "Also, mastication on one side only has been shown to affect BDNF gene expression in the hippocampus, with cognitive impairment evaluated using the Morris Water Maze test in young adult male mice [92•]." (PMID 35764750, 2022). "Acute stress might modulate the anesthesia-related cognitive disorder via targeting the hippocampal brain-derived neurotrophic factor (BDNF)." (PMID 36518560, 2022). "Indeed, AD patients with mild to medium cognitive impairments commonly exhibit increased levels of proBDNF in cortex, hippocampus and cerebrospinal fluid (CSF) on the expense of reduced mature BDNF." (PMID 36397124, 2022). "We wondered whether BDNF/NT-3 could attenuate the cognitive impairment and AHN inhibition mediated by 3% sevoflurane in aged mice." (PMID 35309893, 2022). "Fisetin attenuated histological injury, MDA levels, inflammasome pathway activation, and the mediated production of cytokines IL-1β and IL-18, apoptosis, as well as increased BDNF expression, and reduced astrocyte, microglial activation, and cognitive deficits following VaD." (PMID 35740470, 2022). "The levels of serum BDNF and TrkB were related to cognitive impairment in children with SDB." (PMID 36683819, 2022). "We reported that supplementation with TrkB receptor agonist 7,8-dihydroxyflavone (1 mg/mL in drinking water) during juvenile and adolescent stages could prevent cognitive deficits as well as reduced BDNF-TrkB signaling in the PFC of adult offspring after MIA." (PMID 34977960, 2022). "Moreover, studies have also shown that enhancement of BDNF signaling cascade alleviates cognitive impairment in diabetic rats and protects against neuronal apoptosis and synaptic plasticity dysfunction under hyperglycemic condition." (PMID 36358486, 2022). "It is known that chronic activation of NF-κB through the expression of a constitutively active form of the kinase NF-κB (IKK2) inhibitor beta-subunit, leading to neuroinflammation and decrease in the BDNF level, which correlates with cognitive impairment and neurodegeneration." (PMID 36005540, 2022). "It has been found that septic patients frequently showed cognitive impairment, owing to the interaction between HS fragments in circulation and brain-derived neurotrophic factor (BDNF), leading to inhibiting BDNF-mediated hippocampal long-term potentiation and inducing cognitive dysfunction." (PMID 35448193, 2022). "The cognitive impairment induced by MSD was associated with a decreased brain-derived neurotrophic factor and an increased Synaptotagmin-1, while EE increased and decreased brain-derived neurotrophic factor and Synaptotagmin-1 in the hippocampus of mice from the MSD+EE group, respectively." (PMID 35910680, 2022). "Additionally, they showed that BDNF is a moderating element in the relationship between the severity of cognitive impairment and DPMS dysfunction." (PMID 36248031, 2022). "We found a profile of progressive cognitive impairment beginning at 3 months of age and becoming profound by 6 months, age dependent decline in BDNF, a neurotrophic protein differentially regulated by NMDARs, and an age dependent increase in markers of epileptiform activity." (PMID 36742045, 2022). "In ASD, loss-of-function mutations in JARID1C, an X-linked gene encoding H3K4 demethylase, may also be associated with cognitive impairment, as it regulates autism and cognitive dysfunction genes such as SCN2A, CACNA1H, BDNF, and SLC18A1." (PMID 36406755, 2022). "It is hypothesized that serum levels of BDNF are lower in AD patients than in healthy controls and subjects with mild cognitive impairment." (PMID 36438603, 2022).
Cognitive impairment (continued). "Therefore, BDNF is a biomarker of cognitive function, and therapeutic approaches targeting the ERK-CREB-BDNF pathway can be an effective strategy in developing potential therapeutics for cognitive impairment." (PMID 36615789, 2022). "Similarly, treating adolescent stress with duloxetine reversed set-shifting cognitive deficits and increased brain-derived neurotrophic factor (BDNF) protein expression in the mPFC)." (PMID 36431303, 2022). "Therefore, this study aimed to explore the effects of CCRT and aerobic exercise on information processing speed, cognitive flexibility, and BDNF in patients with schizophrenia presenting with cognitive impairment." (PMID 36261468, 2022). "Moreover, the evolving literature has shown significant benefits of physical exercise, attenuating cognitive impairment, reducing dementia progression, and increasing brain-derived neurotrophic factor (BDNF) and hippocampal plasticity." (PMID 35741616, 2022). "Therefore, apigenin treatment inhibited scopolamine-induced cognitive impairment by regulating the apoptosis, amyloidogenic and BDNF/TrkB pathways." (PMID 34500626, 2021). "In conclusion, our study is the first step in characterizing reduced peripheral BDNF levels and large-scale cognitive deficits in older schizophrenia, supporting the accelerated aging hypothesis of schizophrenia." (PMID 34239458, 2021). "Furthermore, cognitive impairment can mostly induce a compensatory increase in the processing of pro-BDNF to generate mature BDNF." (PMID 33767621, 2021). "Although long-term cardiac damage after ISO appeared substantial, it did not induce cognitive impairment nor associated changes in microglia or BDNF expression in hippocampal CA1." (PMID 34880374, 2021). "Elevated miR-195 may play a role in regulating BDNF protein expression thereby influencing cognitive impairments in schizophrenia, suggesting that development of cognition enhancing treatment for schizophrenia may consider a micro-RNA based strategy." (PMID 33558459, 2021). "Reduced BDNF concentrations have been reported in the prefrontal cortex and other regions of the brain in schizophrenia and have been speculated to be related to cognitive deficits in schizophrenia." (PMID 33558459, 2021). "Genetic polymorphisms in select genes, including APOE (apolipoprotein E), COMT (Catechol-O-Methyltransferase), MDR1 (multi-drug resistance 1), BDNF (brain derived neurotrophic factor), and GST (glutathione-S-transferase), have been associated with vulnerability to cognitive impairment." (PMID 33731765, 2021). "In conclusion, DW2009 may synergistically or additively increase the effect of donepezil against cognitive impairment and colitis by regulating NF-κB-mediated BDNF expression." (PMID 34579150, 2021). "The findings of the present study indicate that SK may inhibit hippocampal neuron apoptosis and protect against injury induced by CCH by regulating the PTEN/Akt/CREB/BDNF signaling pathway and thereby improve cognitive impairment." (PMID 34211568, 2021). "Similarly, our results together with previous studies, verified that in patients with schizophrenia, cognitive impairments were always accompanied by lower blood BDNF levels." (PMID 34239458, 2021). "Cognitive deficit in schizophrenia has been related to an increase in inflammatory cytokines, to an imbalance in hormones such as cortisol and prolactin, in neurotrophic factors such as BDNF and in neurotransmitters such as GABA and glutamate." (PMID 34576069, 2021). "BDNF overexpression attenuated motor deficits and cognitive impairment in MPTP‐induced PD mice." (PMID 34132500, 2021). "Elevating concentrations of BDNF is therefore a mechanism by which bifidobacteria may prevent cognitive impairment in Aβ1-42-treated mice." (PMID 34064762, 2021). "DC and DD may alleviate cognitive impairment by the regulation of NF-κB-mediated BDNF expression through the attenuation of gut dysbiosis and inflammation." (PMID 34579150, 2021).
Cognitive impairment (continued). "Smoking status significantly affected cognitive performance in controls and in veterans with PTSD, and the presence of the T allele of the BDNF rs56164415 was repeatedly associated with stronger cognitive impairment in both smokers and non-smokers with PTSD." (PMID 33926045, 2021). "Moreover, TrkB/BDNF signaling inhibitor ANA-12 abolished the improving effects of rhANP on LPS-induced cognitive impairment." (PMID 34949194, 2021). "Our observation is consistent with that of El-Morsy and Ahmed16, who suggested that the ability of lycopene to diminish cognitive deficit might be due to attenuation OS and upregulation of BDNF." (PMID 34294819, 2021). "Therefore, hUC-MSCs have the potential to reverse Aβ-induced cognitive impairment through a neuroprotective mechanism mediated by BDNF." (PMID 34899919, 2021). "Also, heparan fragments released from the degrading endothelium glycocalyx of the BBB during sepsis were found to sequester brain-derived neurotrophic factor and impair hippocampal long-term potentiation explaining the resulting cognitive impairment." (PMID 33293688, 2021). "If our hypothesis is correct, patients with low miR195 and high BDNF (↓miR195/↑BDNF) should have the least cognitive impairment while patients with high miR195 and low BDNF (↑miR195/↓BDNF) should have the most severe cognitive impairment." (PMID 33558459, 2021). "However, low blood BDNF concentrations are more consistently identified in adults with Alzheimer’s disease, and less so in adults with mild cognitive impairment." (PMID 34531736, 2021). "However, oral administration of NK210 and/or NK219 decreased cognitive impairment-like behaviors and NF-κB+/Iba1+ cell population in the hippocampus, while BDNF+/NeuN+ cell population increased." (PMID 34667205, 2021). "In a rat model of combined amyloid-beta and isoflurane-induced cognitive impairment, ketamine (2.5, 5, or 10 mg/kg) rescued spatial memory deficits on the Morris Water Maze paradigm and promoted BDNF production through upregulation of the PI3K/AKT/GSK-3β pathway." (PMID 34566558, 2021). "A recent meta-analysis of BDNF levels and cognitive impairment in schizophrenia, that included 21 studies that accounted for a total 2,449 patients with schizophrenia-spectrum disorders, found that BDNF levels were modestly but significantly related to cognitive functioning." (PMID 34220575, 2021). "In clinical studies of elderly people with mild cognitive impairment, an improvement in cognitive function (memory and attention) and an increase in brain-derived neurotrophic factor (BDNF) were reported after treatment with Lactobacillus plantarum C29-fermented soybean for 12 weeks." (PMID 33805484, 2021). "Growing evidences suggested that up-regulation of BDNF can relieve cognitive impairments and learning deficits in AD, while NT3 can promote the proliferation and differentiation of bone marrow-derived NSCs into cholinergic neurons and elevate the levels of acetylcholine (ACh)." (PMID 32948180, 2020). "NSE, BDNF, and NGEF are well-established biomarkers of cognitive impairment in PD patients, indicating that they may play a pathogenic role." (PMID 33329296, 2020). "The hippocampus is an important brain region for learning and memory; thus, abnormal expression of histone acetylation and BDNF in the neonate may induce long-term cognitive deficits." (PMID 32813852, 2020). "Moreover, decreased BDNF expression likely alters synaptic plasticity, ultimately leading to cognitive impairment in an elderly individual following prenatal mobile phone exposure." (PMID 32581772, 2020). "Prenatal long-term mobile phone exposure may aggravate cognitive impairment in the aged rat offspring by modulating the synaptic plasticity and BDNF expression." (PMID 32581772, 2020). "Moreover, alterations in BDNF levels are correlated with the cognitive impairment observed in several neurological diseases." (PMID 32349283, 2020).
Cognitive impairment (continued). "Levels of circulating BDNF protein can be established from blood samples and have been reported to be reduced in psychiatric conditions as well as in individuals with mild cognitive impairment (MCI;), the latter proposed to be a potential precursor state for AD." (PMID 32218234, 2020). "Short term treatment with CBD in mice model of BCCAO has been shown to prevent motor and cognitive impairment through a complex mechanism related with stimulation of synthesis in the hippocampus of the levels of BDNF and MAP-2 proteins and stimulation of neurogenesis." (PMID 32726998, 2020). "For example, decreased H3K9 methylation in the hippocampus have been found in aged rats; BDNF, cFOS, and deoxyribonucleic-acid-methyltransferase-3a (DNMT3A), all of which were associated with cognitive impairment during the aging process, also undergo expression alterations." (PMID 33192481, 2020). "Our goal was to examine whether multicomponent exercise performed by older adults with mild cognitive impairment or dementia as group-based exercise in community have beneficial effects on cognition and brain-derived neurotrophic factor." (PMID 32191630, 2020). "P021 was shown to rescue cognitive impairment in rodent models of AD via increased BDNF expression." (PMID 32854771, 2020). "However, enhancement of the BDNF/TrkB pathway alleviates cognitive impairment in diabetic rats and protects against neuronal apoptosis and synaptic plasticity dysfunction under HG conditions." (PMID 32425784, 2020). "In the present study, we tested the hypothesis that AOM could induce adult hippocampal neurogenesis and improve poststroke cognitive impairment via inducing brain-derived neurotrophic factor (BDNF) signaling pathway." (PMID 33537297, 2020). "Herein, we tested the hypothesis that AOM could induce adult hippocampal neurogenesis and improve poststroke cognitive impairment via inducing BDNF/TrkB/AKT signaling pathway." (PMID 33537297, 2020). "In our previous study, we demonstrated that anesthesia and surgery could induce microglial activation, I L-1β release, and BDNF downregulation in the hippocampus and thus resulted in hippocampus-dependent cognitive impairments in aged mice." (PMID 31948437, 2020). "Sevoflurane regulates neurogenesis in offspring rats by down-regulating the expression of brain-derived neurotrophic factor (BDNF), which is the critical neural development and disease related gene and induces neurotoxicity and cognitive impairment in young mice." (PMID 32793611, 2020). "Moreover, a persistent reduction in hippocampal BDNF levels in adult rats that were neonatally exposed to isoflurane results in the insufficient synthesis of synaptic proteins and contributes to the cognitive impairment." (PMID 32148659, 2020). "Apelin-13 (i.c.v.)alleviated memory performance deficits in a rat model of chronic water-immersion restraint stress and cognitive deficits in a streptozotocin-induced rat model of Alzheimer’s disease, each of which was mediated by brain-derived neurotrophic factor (BDNF) signaling." (PMID 33013308, 2020). "Cardiac up-regulation of miR-1 induced cognitive impairment, which may be correlated with the down-regulation of hippocampal BDNF level." (PMID 31217927, 2019). "The BDNF level has been found to be decreased in the brain of AD postmortem samples and AD animal models, and defective BDNF is involved in the synaptic dysfunction and cognitive impairment in AD, while the upregulation of the BDNF pathway can reverse these phenomena." (PMID 30867903, 2019). "Therefore, these neurochemical results lead us to assume that PQM130 may activate the BDNF signaling pathway and thus control the expression of its downstream signaling components and the structural proteins associated to synaptic plasticity in the hippocampus, improving cognitive deficits in mice." (PMID 31244664, 2019).